NPAS3 (neuronal PAS domain protein 3)
Diseases named in the same sentence as NPAS3 in open-access papers (continued):
Sharing a sentence is not in itself a finding about the gene and the disease.
developmental delays (1 paper, 2021). "NPAS3 214fs is the third variant identified in an individual with developmental delay or ID that truncates or deletes part of NPAS320,27, however, it is the first such variant that has been characterised and shown to cause a loss of function." (PMID 33758288, 2021). "The available patient data indicate that most younger patients with NPAS3 variants (2/2 individuals with G229R and 2/3 individuals with G201R) present with developmental delays, including speech and/or motor delays, which can be indicative of later intellectual disability." (PMID 33758288, 2021). "Therefore, we have identified the first variant in NPAS4 identified in an individual with developmental delay, as well as the third NPAS3 variant in an individual with developmental delay/ID, further establishing NPAS3 and NPAS4 as candidate neurodevelopmental disorder genes." (PMID 33758288, 2021). "In summary, two loss-of-function variants NPAS3 214fs and NPAS4 170X, were identified in individuals with either ID or developmental delay." (PMID 33758288, 2021). "Here we have identified loss-of-function variants in both NPAS3 and NPAS4 in individuals with ID and developmental delay respectively, further establishing them as candidate neurodevelopmental disorder genes." (PMID 33758288, 2021). "From a clinical exome sequencing database we identified three NPAS3 variants and four NPAS4 variants that could potentially disrupt protein function in individuals with either developmental delay or ID." (PMID 33758288, 2021). "Therefore, we identified individuals from a clinical exome sequencing database who possessed a NPAS3 or NPAS4 variant that may reduce transcriptional activity and a phenotype that included either ID or developmental delay." (PMID 33758288, 2021). "One individual identified with a NPAS3 G201R variant did not present with developmental delay, however as low penetrance alleles may exist, the variant was still characterised." (PMID 33758288, 2021).
diabetes (1 paper, 2015). "This conclusion is supported by previous studies of NPAS3, where gene mutations are related to the aerobiology of psychiatric illness and the gene can induce susceptibility to diabetes for psychiatric patients." (PMID 25898945, 2015). "Therefore, the component gene of NPAS3 and TFs of FOXO4 and POU2F1 can form another hypothesis of potential genetic pathways related to diabetes pathogenesis." (PMID 25898945, 2015).
holoprosencephaly (1 paper, 2018). Holoprosencephaly (HPE) is a complex brain malformation resulting from incomplete cleavage of the prosencephalon, occurring between the 18th and 28th day of gestation, and affecting both the forebrain and face, which results in neurological manifestations and facial anomalies of variable severity. "Large scale deletions including NPAS3 have been associated with holoprosencephaly, holoprosencephaly microform and other gross neurodevelopmental abnormalities." (PMID 30509165, 2018).
Insulin resistance (1 paper, 2013). Increased resistance towards insulin, that is, diminished effectiveness of insulin in reducing blood glucose levels. "Variants of genes AKAP6, NPAS3, MARCH6 and FBXL7 have been previously reported to be associated with insulin resistance, inflammatory markers or adiposity studies using genome-wide approaches whereas associations of CDH18 and MYO10 with MetS traits have not been reported before." (PMID 23628382, 2013).
lung carcinoma (1 paper, 2023). "Some known lung cancer susceptibility loci were also showed association with trajectory scores, such as NPAS3 locus (rs7154051, significant level P = 1.19e-07), DSCAM locus (rs1569094034, significant level P = 5.54e-07) and VLDLR-AS1 locus (rs7029746, significant level P = 1.15e-06)." (PMID 37228122, 2023). "Our result showed that several loci, such as PARVA locus and NPAS3 locus, were also mentioned in large-scale lung cancer GWAS study." (PMID 37228122, 2023).
prostate carcinoma (1 paper, 2016). A carcinoma that arises from epithelial cells of the prostate gland. "Together, these data indicate that the rs8004379 C allele might be associated with increased expression of NPAS3 and decreased risk of recurrence and mortality in prostate cancer patients after treatment." (PMID 26902966, 2016). "Furthermore, gene expression survival analyses showed that higher levels of NPAS3 correlated with improved outcomes for prostate cancer patients." (PMID 26902966, 2016). "We hypothesized that NPAS3 might have an important role in prostate cancer progression." (PMID 26902966, 2016).
psychosis (1 paper, 2023). "NPAS3, RBM38, and PELI1 were associated with the risk of AD in APOE4 (-) individuals and AD with psychosis in a European cohort." (PMID 36982982, 2023).
psychiatric disorder (16 papers, 2013 to 2025). A disorder characterized by behavioral and/or psychological abnormalities, often accompanied by physical symptoms. "NPAS3 regulates adult hippocampal neurogenesis and exhibits circadian-dependent transcriptional activity; dysfunction of NPAS3 impairs neurogenesis in the hippocampal subgranular zone and has been linked to psychiatric disorders." (PMID 41515962, 2025). "Some genetic studies have also shown a possible association of NPAS3 with severe psychiatric disorders." (PMID 36430976, 2022). "As the four genes (CSMD1, PTPRD, LSAMP, and NPAS3), which remained significant also in the sex-specific analyses, have previously been implicated in other psychiatric disorders, pleiotropic effects could also be suggested." (PMID 39457114, 2024). "In fact, V304I was identified as an NPAS3 missense variant associated with psychiatric disorders." (PMID 33799876, 2021). "Besides GRID1, top markers mapped to within or near NPAS3, which potentially regulates genes involved in neurogenesis and has been previously associated with psychiatric disorders; and SV2B, a synaptic vesicle protein-encoding gene implicated in cognitive processes in model systems." (PMID 28360924, 2017). "Revealing the regulation of NPAS3 on VGF and the precise mechanism of how NPAS3 influences neural cell proliferation will increase our understanding of pathophysiological mechanisms of psychiatric disorders." (PMID 27877109, 2016). "Npas3 knockout mice display a range of behavioral phenotypes consistent with it being a representative model of human psychiatric disorders." (PMID 27877109, 2016). "NPAS3 knockout mice also display an additional deficit in adult hippocampal neurogenesis and aberrations in synaptic transmissions, but the underlying mechanism of dysfunctions of neurogenesis and synaptic activity in relation to the pathology of psychiatric disorder is currently unknown." (PMID 27877109, 2016). "Our published metabolomics study of brain tissue from a mouse model of psychiatric disorder, the Npas3 knockout, also showed elevated levels of sedoheptulose (2.65-fold increase)." (PMID 27076878, 2016). "Variants in NPAS3 have since been associated with several major mental illnesses and response to an antipsychotic, while mice lacking the Npas3 gene also display behavioral abnormalities." (PMID 34834422, 2021). "We therefore set out to determine whether aggregation of NPAS3 may be a general phenomenon of major mental illness, and if it is present in a greater subset of individuals than would be predicted by the rare V304I mutation." (PMID 34834422, 2021). "The second part of the review addresses the known proteins whose aggregation in brain tissue has been observed in psychiatric disorders (amyloid, tau protein, α-synuclein, DISC-1, disbindin-1, CRMP1, SNAP25, TRIOBP, NPAS3, GluA1, FABP, and ankyrin-G)." (PMID 36430976, 2022). "Neuronal PAS domain protein 3 (NPAS3) and VGF (VGF Nerve Growth Factor (NGF) Inducible) are important for neurogenesis and psychiatric disorders." (PMID 27877109, 2016). "This network collectively detailed how NPAS3 connects with VGF and intersected neural cell proliferation, synaptic activity and psychiatric disorders." (PMID 27877109, 2016). "The findings in this study indicate a correlation between NPAS3 and VGF, and propose a potential network composed by NPAS3, VGF and several other pivotal factors relevant to neurogenesis and psychiatric disorders." (PMID 27877109, 2016). "We have previously determined that aggregation of TRIOBP-1, another protein implied to aggregate in mental illness, occurs specifically through one structural region, and it is therefore possible that aggregation of non-mutant NPAS3 is also driven by a specific structural feature." (PMID 34834422, 2021). "Therefore, NPAS3 and VGF might function to orchestrate the molecular response during the processes of neurogenesis and psychiatric disorders." (PMID 27877109, 2016).
neurodevelopmental disorder (6 papers, 2018 to 2024). A behavioral and cognitive disorder with onset during the developmental period that involves impaired or aberrant development of intellectual, motor, or social functions. "Our results can also be used to inform the likely functional consequences of other NPAS3/4 variants identified in individuals with SZ or neurodevelopmental disorders." (PMID 33758288, 2021). "TFs associated with neurodevelopmental disorders, such as Npas1 and Npas3, are preferentially expressed in DR-6, and Aff2 is enriched within DR-3." (PMID 31647409, 2019). "NPAS3 encodes a transcription factor which has been associated with multiple human psychiatric and neurodevelopmental disorders." (PMID 30509165, 2018). "This adds to the growing literature that implicate NPAS3 variants in neurodevelopmental disorders." (PMID 33758288, 2021). "This provides evidence that a heterozygous loss-of-function in NPAS3/4 may contribute to neurodevelopmental disorders." (PMID 33758288, 2021). "This includes the NPAS3 gene, with the most differentiated DMS found overall, which coordinates neurogenesis and has been associated with neurodevelopmental disorders when dysregulated." (PMID 39286762, 2024). "Npas3 belongs to a group of transcription factors called basic helix-loop-helix (bHLH) PAS family and has been associated with psychiatric and neurodevelopmental disorders." (PMID 37569835, 2023). "The neuronal PAS domain 3 (NPAS3) is a member of the basic helix-loop-helix (bHLH) PAS family of transcription factors and is implicated in psychiatric and neurodevelopmental disorders." (PMID 36313621, 2022). "In support of the implication of NPAS3 in neuropsychiatric and neurodevelopmental disorders, mouse knockout models of Npas3 display a range of behavioral phenotypes including locomotor hyperactivity, subtle gait defects, memory problems, and impairment of prepulse inhibition." (PMID 36313621, 2022). "The identification of additional NPAS3 and NPAS4 variants will further our understanding of rare variants that may contribute to SZ or neurodevelopmental disorders which could then assist in patient diagnosis." (PMID 33758288, 2021). "This further establishes NPAS3 and NPAS4 as candidate neurodevelopmental disorder genes." (PMID 33758288, 2021). "To date, the involvement of NPAS3 and NPAS4 in neurodevelopmental disorders has not been extensively explored." (PMID 33758288, 2021).
tumor (6 papers, 2013 to 2025). "NPAS3, a transcription factor, has a tumour-suppressive role in manipulating the progression of certain types of cancer." (PMID 40535770, 2025). "The SNP rs8004379 is also located within an intron of the NPAS3 gene, encoding a member of the neuronal PAS transcription factor gene family, which has diverse roles including neurobehavior and tumor development." (PMID 26902966, 2016). "NPAS3 can also modulate cell cycle proliferation, apoptosis, migration and cell invasion and exhibits features of a tumor suppressor." (PMID 23628382, 2013).
cancer (3 papers, 2013 to 2025). A tumor composed of atypical neoplastic, often pleomorphic cells that invade other tissues. "Shared pseudotemporally correlated genes between both integrated datasets included genes associated with proliferation (CENPF and TOP2A), cancer‐associated fibroblasts (DCN and COL1A1) and neurodevelopment (HMGB2 and NPAS3)." (PMID 39836549, 2025). "We discovered the greatest nicotine stress response by HPCAL4 (up-regulated by 4.71 fold) and NPAS3 (down-regulated by -2.73 fold); both are genes that have not been previously implicated in nicotine exposure but are linked to cancer." (PMID 23825647, 2013). "NPAS3 is a member of the neuronal PAS transcription factor gene family, which has a variety of functions, including cancer development and neurobehaviour." (PMID 40535770, 2025).
neurodegenerative disease (2 papers, 2024 to 2025). A disorder of the central nervous system characterized by gradual and progressive loss of neural tissue and neurologic function. "This would further imply that increasing 3222401L13Rik expression or strengthening the interaction of 3222401L13Rik and Npas3 in early aging processes or at the onset of neurodegenerative diseases such as AD could be a potential clinical option to delay the onset of neuronal dysfunction." (PMID 39846680, 2025).
cardiovascular disease (1 paper, 2020). "NPAS3 (Neuronal PAS Domain Protein 3) rs8008403 has not been previously associated with cardiovascular disease related outcomes, but another variant in NPAS3 (rs17460823) was associated with C-reactive protein in patients taking fenofibrate." (PMID 33171725, 2020).
genetic disorder (1 paper, 2021). "However, it is possible that in other individuals with a suspected genetic disorder, a loss-of-function for NPAS3 may contribute to a syndromic form of ID." (PMID 33758288, 2021).
neurological diseases (1 paper, 2021). "Interestingly, the gene that accumulates the largest number of HAR in the human genome is the neurodevelopmental transcription factor NPAS3 (Neuronal PAS domain-containing protein 3), a gene that has been associated with several neurological diseases in humans." (PMID 33659245, 2021).
NPAS3 also shares sentences with these, for which no sentence is quoted: autism spectrum disorder (2 papers); mood disorder (2); Alzheimer disease (1); Anxiety (1); Auditory hallucination (1); autism (1); brain cancer (1); COVID-19 (1); glioma (1); learning disability (1); mental disorder (1); Motor delay (1); Sotos syndrome (1); substance abuse (1); triple-negative breast carcinoma (1).